MS4A1 (membrane spanning 4-domains A1)
Diseases named in the same sentence as MS4A1 in open-access papers (continued):
Sharing a sentence is not in itself a finding about the gene and the disease.
emphysema (1 paper, 2021). "We identified a series of significant pathways, including BCR signaling pathway, ECM-related pathways, NF-κB and TGF-β signaling pathways, and several hub genes (i.e. CD19, BLK, MS4A1, POU2AF1, and COL6A1) that may be involved in the emphysema phenotype of COPD." (PMID 33535173, 2021).
low grade glioma (1 paper, 2020). A grade I or grade II glioma arising from the central nervous system. "Here, we show that MS4A1 and TIL-B are consistently prognostic in 5 cancers (head and neck, lung, cervical, kidney and low-grade glioma), while unexpectedly, CD20 protein levels lack quantitative correlations with MS4A1/TIL-B levels and demonstrate limited prognosticity." (PMID 32398659, 2020).
lymph-node metastasis (1 paper, 2020). "MS4A1 was expressed higher in women and the older (>65 years), stage N0, stage T1&T2, and stage I&II patients, while in the patients with lymph-node metastasis and advanced TNM stage, OAS1 had higher expression." (PMID 32850406, 2020).
nasopharyngeal carcinoma (1 paper, 2022). A carcinoma arising from the nasopharyngeal epithelium. "In nasopharyngeal carcinoma, a higher expression of MS4A1 was associated to a longer progression free survival." (PMID 36157879, 2022).
sarcoidosis (1 paper, 2024). Sarcoidosis is a multisystemic disorder of unknown cause characterized by the formation of immune granulomas in involved organs. "(e) Finally, sarcoidosis-associated B cells expressed MS4A1 (also known as CD20), FCER2 (also known as CD23), BCL6, and AICDA, which are all markers of late-stage differentiated B cells in mature TLSs." (PMID 39225100, 2024).
sarcoma (1 paper, 2024). A usually aggressive malignant neoplasm of the soft tissue or bone. "For example, CD20/MS4A1 expression can be used as a prognostic tool for sarcoma survival prediction, but not in patients with a markedly immunosuppressive tumor microenvironment." (PMID 38240704, 2024).
seminoma (1 paper, 2023). A radiosensitive malignant germ cell tumor found in the testis (especially undescended), and extragonadal sites (anterior mediastinum and pineal gland). "To further examine the functions of MMP9 and CTSK in seminoma, we subset immune cells (PTPRC+), and explored the expression patterns of markers for T cells (CD3D+ and CD3E+) and B cells (CD79B+; MS4A1+ and SDC1+)." (PMID 38123589, 2023).
soft tissue sarcoma (1 paper, 2019). A malignant neoplasm arising from muscle tissue, adipose tissue, blood vessels, fibrous tissue, or other supportive tissues excluding the bones. "Analysis of CD20/MS4A1 expression in soft tissue sarcoma merits further attention as a promising candidate prognostic tool for survival, but not in patients with a pronounced immunosuppressive tumor microenvironment." (PMID 30879106, 2019).
systemic sclerosis (1 paper, 2025). A chronic disorder, possibly autoimmune, marked by excessive production of collagen which results in hardening and thickening of body tissues. "The vast majority (92.8%) of the systemic sclerosis IGHM-expressing B cells expressed MS4A1 (CD20), which is the typical expression pattern for IGHM-expressing B cells." (PMID 39989459, 2025).
vasculitis (1 paper, 2024). "MS4A1, commonly known as CD20, plays a pivotal role in the pathogenesis of Kawasaki Disease (KD), a principal cause of acquired pediatric heart disease characterized by vasculitis primarily affecting the coronary arteries." (PMID 39239552, 2024).
tumor (70 papers, 2012 to 2026). "Genes with protective roles, MS4A1, showed significant associations with the presence of anti-tumor immune cell infiltration levels." (PMID 41488652, 2025). "Our study identified and validated the efficacy of SLC16A6, CCR7, and MS4A1 as tumor suppressors implicated in AML progression and related to immune cell infiltration." (PMID 41036204, 2025). "Furthermore, MS4A1 has been implicated as a positive prognostic factor concerning tumor microenvironment, tumor invasion, and immunological responses." (PMID 40486872, 2025). "These upregulated genes (Cdkn1a, Eda2r and Phlda3), are known for their role in cell cycle arrest, apoptosis and tumor suppression, while the most downregulated genes (Hba-a2, Serpina9, and Ms4a1) are associated with hemoglobin synthesis, mitochondrial function and B cell differentiation 34–43." (PMID 36604457, 2023). "SYNE1 is associated with both an increased tumor mutation burden and overexpression of MS4A1." (PMID 37762518, 2023). "Interestingly, nivolumab-bound T cells had higher expression of MS4A1 than unbound T cells suggesting a mechanism for downregulation of CD20 in tumour-associated T cells is via the PD ligand 1-PD1 pathway." (PMID 35951029, 2022). "In conclusion, our study identified and validated CCR7, SLC16A6, and MS4A1 as tumor suppressors involved in the development of AML and related to immune cell infiltration." (PMID 41036204, 2025). "In analyzing B cells in the tumor microenvironment, B cells were separated into two clusters: one termed as follicular B cell, with high expressions of MS4A1, CD79B, CD52, and another termed as plasma cell, with high expressions of IGHG1, IGHG4 and MZB1." (PMID 38443340, 2024). "The role of MS4A1 in tumor progression is still in the initial stage of research and is worthy of further exploration." (PMID 37604869, 2023). "As shown by analysis based on variable regions of light chain, most BCR were shared across the tumor stages, and MS4A1+ follicular B cells and IgA+ plasma cells obtained the most diverse variable regions." (PMID 37360193, 2023). "MS4A1 is a B-lymphocyte antigen, which is a one of the most commonly used biomarkers for tumor-infiltrating B-lymphocytes." (PMID 36157879, 2022). "As far as we know, this study is the first in vitro experiment to show that MS4A1, as a tumour suppressor gene, can inhibit the progression of CC." (PMID 36203424, 2022). "Tumor immune cells (PTPRC/CD45+) also consisted of B cells (MS4A1/CD20+), plasma cells (XBP1+), macrophages (CD14+), dendritic cells (CD80+, CD86+), and mast cells (TPSAB1+)." (PMID 35742914, 2022). "The SIRPA‐CD47, CXCL12‐DPP4, and NRG1‐ERBB3 interactions were found between MS4A1+ B cells and epithelial cells in tumor." (PMID 33463049, 2021). "We identified that the expression of MS4A1 (CD20) were higher in tumor tissues compared to adjacent normal tissues and the expression level of MS4A1 was significantly decreased in the advanced stages of lung cancers." (PMID 32580738, 2020). "The prognostic role of MS4A1 expressing B cells was only observed in an IL10low, PTGS2low or CD163low tumor microenvironment according to the transcriptomic data." (PMID 30879106, 2019). "Altogether, these data indicated that the observed prognostic impact of MS4A1 expression is altered by the immune profile of the tumor microenvironment." (PMID 30879106, 2019). "However, the potential mechanism of CD8 + T cells participating in MS4A1-mediated tumour inhibitory effect remains to be further studied." (PMID 36203424, 2022).
tumor (continued). "After further study, it was noticed that MS4A1 was related to lower cancer stem cell score, and our study revealed for the first time that MS4A1 may be a potential tumour suppressor gene in CC." (PMID 36203424, 2022). "MS4A1 was found in the signature genes of “tumor-infiltrating lymphocytes (TIL)”." (PMID 34395521, 2021). "However, to what extent the listed genes that correlated with MS4A1 are involved in B cell function in the tumor microenvironment remains to be explored." (PMID 30879106, 2019). "Because MS4A1 encodes the CD20 B lymphocyte marker, the origin of its up regulation in ARLC-SCC which comprises primary tumor cells as well as stroma was explored using immunohistochemistry to determine if deregulation was due to stromal lymphocytes rather than lung tumor cells." (PMID 22514692, 2012). "For our purposes, tumor cell enrichment by microdissection may have avoided the emergence of dominant signals from stromal elements, as illustrated by identification of MS4A1 as a gene of interest." (PMID 22514692, 2012). "Additionally, we proved that MS4A1 was highly correlated with the immune infiltration of tumor, so we assumed that MS4A1 may improve patient prognosis by regulating immune homeostasis." (PMID 41036204, 2025). "In this study, we identified and validated three tumor suppressors (SLC16A6, CCR7, and MS4A1) in AML; they were markedly reduced in AML patients." (PMID 41036204, 2025). "Integrated characterization of tumor and immune features, a four-gene prognostic signature comprising CD276, MS4A1, IGFBP1, and CD200 was established." (PMID 41488652, 2025). "In particular, based on high level of SDC1, TNFRSF17, MZB1, CD38 and low level of CD19 and MS4A1, Cluster 0, Cluster 1 and Cluster 12 were defined as SDC1+ cells, namely plasma cell in HD controls and tumor cells in MM patient." (PMID 36532059, 2022). "Second, the survival analysis showed that 7 genes had significant (p < 0.05) Kaplan–Meier curves, including 5 genes (MS4A1, N4BP2L1, IGF1R, TCF7L2 and COL11A1) based on the normal expression, and 2 genes (TCF7L1 and PTPRM) based on the tumor expression." (PMID 35406404, 2022). "Patients with CC with high MS4A1 and TNFRSF17 expression had lower stemness scores, which further indicates that MS4A1 and TNFRSF17 can act as tumour suppressor genes." (PMID 36203424, 2022). "Consistent with all above the results, immune-related genes were highly expressed in hot tumor, for instance, CXCL9, TCL1A, CCL19, CXCL13, MS4A1, and C4orf7." (PMID 33816503, 2021). "Among them, 14 clusters were mature B cells (with nine subsets from tumor lesion and five clusters from peripheral blood), which are characterized by highly expression of CD20 (MS4A1)." (PMID 34489408, 2021). "The gene expression results showed that the expression levels of MS4A1 and KRT6A in tumour tissues were higher than in normal tissues, while CRTAC1 expression in tumour tissues was lower than in normal tissues." (PMID 34060213, 2021). "The results showed that the expression levels of MS4A1 and KRT6A in tumour tissues were higher than in normal tissues, while CRTAC1 expression in tumour tissues was lower than in normal tissues." (PMID 34060213, 2021). "Several of these markers including MS4A1, CXCR5, and CXCL13 are also suppressed across all stages (Stages 1–4) with respect to normal, further emphasizing their role in sustaining tumor behavior within LSCC." (PMID 32293332, 2020). "Here, we integrated and refined TCGA sourced tumor-related DEGs with genes from TISIDB related to immune to ultimately establish a four-gene prognostic signature comprising CD276, MS4A1, IGFBP1 and CD200, which has the ability to reflect ICIs responses and survival outcomes." (PMID 41488652, 2025). "The MS4A1 gene, which encodes the CD20 protein, is active in both normal B cells and tumor B1 and B2 cells, with higher expression in Tumor B2 compared to normal B cells and Tumor B1." (PMID 41238550, 2025).
tumor (continued). "When ranking the tumor specificity of 13,350 genes with protein information in ascending order, targets falling within similar tumor specificity (BayesTS = 0.02) as the well-known targets (e.g., MAGEA1, MS4A1) can be selected for further evaluation." (PMID 39515334, 2024). "Humoral immunity in relation to tumor progression has not been as thoroughly researched, but, according to a few studies, it seems that CD20+ (MS4A1+) B cells are associated with better prognosis." (PMID 36800011, 2023). "Reclustering revealed 11 distinct subclusters, of which nine were enriched in tumor and interface zones and designated as plasma B cells (clusters 2 and 10, IGHG1 +), follicular B cells (clusters 0, 3, 6, 8 and 9, MS4A1 +), immature B cells (cluster 7, IL7R +) and mast cells (cluster 5, TPSAB1 +)." (PMID 37644609, 2023). "Moreover, the B‐cell marker MS4A1 was upregulated, and the plasma cell marker JCHAIN was downregulated in early CRC tumor." (PMID 33463049, 2021). "The neutral effect of both IGHG1/MS4A1 ratio and IgG1 clonality in KRASmut tumors suggests that IgG1-producing plasma B-cells do not play a prominent role as key drivers of anti-tumor response via ADCC in this subtype of LUAD." (PMID 31665076, 2019). "Tumor samples with a positive HPV status expressed significantly higher levels of all of the B cell-related genes analyzed, namely, BLK, CD19, CR2, HLA-DOB, MS4A1 and TNFRSF17." (PMID 31623665, 2019). "As we also found MS4A1 to be overexpressed in ARLC-ACs, we selected this gene for biological validation in independent test sets (one internal, and one external dataset (2 primary tumor sets))." (PMID 22514692, 2012). "We also found MS4A1 encoding the B-lymphocyte marker CD20, to be up-regulated in ARLC (both SCC and AC), and traced this signal to stromal lymphocytes rather than tumor cells." (PMID 22514692, 2012). "Since the presence of tumor-infiltrating B cells was usually correlated to better overall survival and treatment outcomes, we selected several representative B-cell signatures (CD79A, MS4A1, IGHD, and FCRL4) and examined their prognostic values in NPC patients." (PMID 33750785, 2021). "The TNM stage of patients may be easy to obtain, while the acquisition of another predictor (risk score) required knowledge of the expression of four immune-related genes (MAL, MS4A1, OAS1, and WFDC2) in tumor tissues, which undoubtedly increased the burden of nomogram application." (PMID 32850406, 2020). "While lymphoid aggregates alone did not distinguish between responsive and non-responsive tumours, the integrated analysis revealed higher expression of genes like CD37, MS4A1, BLK, CD79A/B, and TNFRSF13C in responsive tumours’ lymphoid aggregates." (PMID 40141092, 2025). "Our results demonstrated that CXCL13, FCRLA, MS4A1, and PLA2G2D have a negative correlation with tumor purity in OC." (PMID 34395521, 2021).
cancer (38 papers, 2018 to 2025). A tumor composed of atypical neoplastic, often pleomorphic cells that invade other tissues. "SEMA3A was downregulated in all the cancers in which it was differentially expressed, while the regulation of CR2 and MS4A1 varied according to cancer type." (PMID 36497424, 2022). "At both the mRNA level and the protein level, the levels of ZBTB7C, TPSB2, MS4A2, CD19, and MS4A1 in CRC tissues were lower than those in normal tissues adjacent to the cancer." (PMID 33946045, 2021). "The results showed that MS4A1 gene is a protective gene in most cancer types, and the high expression of MS4A1 gene has a better prognosis." (PMID 34060213, 2021). "Of the 23 immune-related prognostic genes identified in LUAD, 7 were reported to be associated with the progression of NSCLC or other cancers, such as ICAM3, MS4A1, and IL-16." (PMID 32209727, 2020). "Additionally, COX5B and MS4A1 were notable for their prognostic relevance across three cancer types." (PMID 40396172, 2025). "From these clusters, five major cell types were identified via classical cell markers, including T cells (CD3E, CD8A, CD3D), B cells (CD19, MS4A1, CD79A), myeloid cells (CD14, CD68, LYZ), endothelial cells (PECAM1, VWF, CDH5) and cancer-associated fibroblasts (CAFs) (ACTA2, FAP, PDGFRB)." (PMID 39941131, 2025). "These genes may serve as potential therapeutic targets and prognostic indicators for improving rituximab sensitivity and reversing drug tolerance in cancer cells, given their significant role in regulating MS4A1 expression in hypoxic DLBCL tumors." (PMID 41189944, 2025). "Moreover, MS4A1 has been shown to have a correlation with the lipid metabolism and immune microenvironment status of individuals with cancer, which suggests its potential as an independent prognostic indicator." (PMID 38342890, 2024). "Although the role of MS4A1 in cancer remains unclear, bioinformatic studies have revealed the prognostic role of MS4A1 in various cancers and its correlation with immune cell infiltration." (PMID 36203424, 2022). "MS4A1 encodes a B-lymphocyte surface molecule CD20 that has been reported to be associated with lipid metabolism and immune cell activation, and its expression is an independent predictor of cancer prognosis." (PMID 36685857, 2022). "As a single gene, detection of GPR18 mRNA could be more versatile than MS4A1 mRNA for pan-cancer prognosis (predictive in nine vs. six cancer types, respectively)." (PMID 32398659, 2020). "We found that MS4A1 was down-regulated in CC, of which low expression predicted the poor prognosis of CC, which indicates that MS4A1 may be a potential biomarker for predicting cancer progression." (PMID 36203424, 2022). "Unbiased clustering using UMAP identified several cell types, including KRT19+ cancer cells, CD3E+ T cells, MS4A1+ B cells, MZB1+ plasmablasts, FLT3+ dendritic cells (DCs), and PROX1+ LECs, which were then visualized within the tissue context." (PMID 41249124, 2025). "Upregulation of MS4A1, IGLL1, RAG1, and SEMA3A resulted in significantly decreased survival in pediatric cancer patients." (PMID 36497424, 2022). "Differential expression analysis with the limma-voom pipeline highlighted multiple genes, CR2, MS4A1, and SEMA3A, which should be further analyzed, given their prevalence among multiple cancer types." (PMID 36497424, 2022). "Driven by our HNSCC findings above, we sought to examine the prognosticity of CD20 proteins vs. MS4A1 mRNA and TIL-B levels across all human cancers in the databases." (PMID 32398659, 2020). "In conclusion, quantitative levels of GPR18, MS4A1, and TIL-B are reliable biomarkers for intratumoral B-cell assessments over CD20 protein, especially for prognostic purposes in cancer." (PMID 32398659, 2020). "In pan-cancers, GPR18 mRNA expression levels demonstrated extremely significant Pearson correlations (Pearson R values) with MS4A1 and TIL-B levels across all 29 cancer types, except for DLBC and UVM (R > 0.2, P < 0.0001)." (PMID 32398659, 2020).